CD4 (CD4 molecule)
Diseases named in the same sentence as CD4 in open-access papers (continued):
Sharing a sentence is not in itself a finding about the gene and the disease.
lupus (continued). "Further, chronic stimulation of the epigenetically altered CD4+CD28+KIR+ T cells found in lupus patients may contribute to their conversion to senescent CD4+CD28−KIR+ T cells." (PMID 28239687, 2016). "Importantly, we find ICER overexpressed in CD4+ T cells from patients with systemic lupus erythematosus." (PMID 27680869, 2016). "In addition, a homeostatic imbalance of Tregs and conventional T cells has been described in experimental lupus, and the transfer of CD4+CD25+Foxp3+ Tregs was reported to prolong drug-induced remission." (PMID 25890083, 2015). "Taken together, hypomethylation of pro-apoptotic genes in naïve CD4+ T cells from healthy African-Americans may contribute to the increased frequency and severity of lupus in African-Americans." (PMID 26609326, 2015). "Compared to MRL/lpr mice, MRL/lpr-p21tg mice showed clear improvement in critical aspects of lupus-like kidney disease such as lower immune complex deposition, decreased inflammatory infiltration of CD4+ T cells and F4/80+ macrophages, and reduced glomerulonephritis." (PMID 25573673, 2015). "Interestingly, numbers of mature splenic T cells (CD3+CD4+/CD3+CD8+) were also elevated in response to disease progression relative to non-lupus animals." (PMID 25974040, 2015). "Global histone H3 and H4 hypoacetylation has been found in lupus CD4+ T cells, and aberrant histone modifications have been observed within the TNFSF7 promoter, leading to CD70 overexpression on T cells, which may contribute to the disease." (PMID 25988383, 2015). "Thus, the systemic lupus-like features observed in scurfy mice appear to be a consequence of Treg dysfunction and uncontrolled CD4+ Teff cell expansion, and, interestingly, a deficiency in Treg number and function has also repeatedly been postulated in human and murine SLE." (PMID 25890083, 2015). "One study found that the overexpression of miR-125 correlates to the reduction of DNMT1 protein expression in lupus CD4+ T cells, and another study reported overexpression of miR-126 in healthy donor CD4+ T cells that led to hypomethylation and overexpression of genes CD11a and CD70." (PMID 25566322, 2014). "We hypothesized that the accumulation of splenic neutrophils in T cell zones of lupus-prone mice may influence CD4+ T cell responses through a BAFF-dependent mechanism." (PMID 25010693, 2014). "We found that Tyro3 and Mer are expressed on CD4+ T cells in some individuals with lupus." (PMID 24650765, 2014). "As the NOD mouse demonstrates susceptibility to a lupus-like syndrome, we investigated whether the aberrancy in the activation profile of CD4 T lymphocytes might be shared with murine models of spontaneous lupus." (PMID 25171173, 2014). "Mer levels correlated with Tyro3 levels on the surface of CD4+ T cells in lupus patients." (PMID 24650765, 2014). "To directly test whether splenic neutrophils from lupus-prone mice affected CD4+ T cell function, we developed a co-culture system to measure neutrophil-mediated CD4+ T cell responses invitro." (PMID 25010693, 2014). "Importantly, estrogen-downregulated miRNAs such as miR-146a and miR-125 were also shown to be depressed in PBMC or CD4+ T cells from human lupus patients and inversely correlated with lupus activity." (PMID 24175965, 2013). "Our data demonstrate that HMGB1 binds to Gadd45a and may be involved in DNA demethylation in CD4+ T cells during lupus flare." (PMID 24082908, 2013). "In lupus, an increase of circulating CD4+CXCR5 + PD-1high T lymphocytes was evidenced in patients with a more severe disease phenotype and a correlation between the expansion of both circulating CXCR5 + Bcl6 + CD4+ T cells and circulating GC B cells was reported." (PMID 24069401, 2013). "The published antibodies (Abs) against CD22 on B cells including Epratuzumab could inhibit B cell activation mainly through binding to C2-set Ig domain of CD22, but they are rarely reported to modulate the pathogenic CD4+ T cell function in systemic lupus erythematosus (SLE)." (PMID 23704998, 2013).
lupus (continued). "In addition, hCDR1 increased the number as well as the function of CD4+CD25+Foxp3+regulatory T-cells in PBMC of lupus patients." (PMID 23555966, 2013). "In consideration to the clinical translation of a Treg-based immunotherapy of SLE, we explored the potential of CD4+Foxp3+ Treg to maintain disease remission after induction of remission with an established cyclophosphamide (CTX) regimen in lupus-prone (NZBxNZW) F1 mice." (PMID 23446139, 2013). "RASGRP1 splice variants have been documented for patients with SLE and abnormal microRNA-driven downregulation of Rasgrp1 expression may play a role in aberrant DNA methylation in Lupus CD4+ T cells." (PMID 24336796, 2013). "Low usage of certain CD4 + TCR Vβ chains was also far more prominent in lupus patients." (PMID 23915345, 2013). "Since the anti- Ro antibody is elevated in many patients with lupus, CD4 (+) cell apoptosis may be decreased in SLE patients." (PMID 24138706, 2013). "In addition, we demonstrated the general importance of CD4+Foxp3+ Treg as physiologically relevant inhibitors of lupus by several approaches." (PMID 23446139, 2013). "Downregulation of DNMT1 in CD4+ T cells contributes to lupus autoreactivity by inducing T cell DNA hypomethylation; this results in the overexpression of autoimmunity-associated genes including lymphocyte function-associated antigen 1 (LFA-1 or CD11a) and CD70." (PMID 23983769, 2013). "Furthermore in other chronic infections such as Trypanosoma cruzi and lupus prone MRL-Fas mice MDSC mediated suppression of CD4+ T cell proliferation." (PMID 24224058, 2013). "Importantly, this study demonstrates the beneficial effects of cystamine on inducing antioxidant activities and CD4+/CD25+ regulatory T cells in lupus-prone mice by decreasing IL-6/STAT3 signalling." (PMID 23905628, 2013). "Infusion of TGF-β-primed CD4+CD25+ cells significantly suppressed the Th1 frequency in lupus mice whereas treatment with atRA/TGF-β-primed CD4+CD25+ cells resulted in the most significant suppression against Th1 cell production in lupus mice." (PMID 21931768, 2011). "The remarkable suppressive function of atRA/TGF-β-induced CD4+ regulatory T cells in lupus mice may be related to the alteration of the phenotypes, stability and functionality of these cells in vivo." (PMID 21931768, 2011). "Furthermore, the levels of IgG, anti-dsDNA and proteinuria were markedly lower in lupus mice treated with atRA/TGF-β-primed CD4+CD25+ cells than in lupus mice treated with TGF-β-primed CD4+CD25+ cells." (PMID 21931768, 2011). "This study tested the hypothesis that CD4+ T cells from systemic lupus erythematosus (SLE) patients exhibited similar defects in Treg induction in response to TGFβ and RA, and that PBX1-d expression is associated with this defect." (PMID 21708033, 2011). "Of interest, CD4+CCR4+CCR6- T cells also appeared to expand in active lupus patients." (PMID 20334681, 2010). "Thus, this study analyzed the balance of CD4+ Th17 and Th1 cell responses in peripheral blood from patients with systemic lupus erythematosus (SLE) and healthy subjects." (PMID 20334681, 2010). "Knowing that γδ T cells express CD40, an important co-stimulation might also occur via CD40L(CD154), which is expressed in a sustained manner at the surface of lupus CD4+ T cells and B cells." (PMID 19390596, 2009). "On the other hand, we have also shown that in B6.129chr1b mice, the CD4+, CD25– T cells were resistant to suppression by regulatory T cells, which suggests a potential new mechanism for the loss of peripheral tolerance in this lupus strain." (PMID 18576325, 2008). "During SLE progression, naïve CD4+ T cells from both adult and pediatric patients exhibited an expanded TIFN cluster, which increases as the lupus disease score, SLEDAI, increases." (PMID 39866877, 2025).
lupus (continued). "It has been demonstrated that systemic lupus erythematosus (SLE) cluster of differentiation 4 (CD4+) T cells have global DNA hypomethylation, contributing to the over-reactivity of T cells in SLE patients." (PMID 40990741, 2025). "Increased glycolysis and mitochondrial respiration have been identified in CD4+ helper T cells from both patients with systemic lupus erythematosus (SLE) and lupus mouse models." (PMID 40693461, 2025). "Altered cellular metabolism in CD4+ T cells has been observed in both patients with SLE and mouse models of lupus." (PMID 40693461, 2025). "Moreover, HDAC1 could promote CD4+T cell hyperactivation in systemic lupus erythematosus by repressing microRNA-124(miR-124) expression through promoter binding." (PMID 40895552, 2025). "It has been demonstrated that animals receiving CD4+ T cells treated with demethylating drugs, such as procainamide and hydralazine, have an illness resembling SLE in mouse models of drug‐induced lupus erythematosus." (PMID 40976999, 2025). "Pharmacological hypomethylation is linked to drug-induced lupus pathogenesis, as evidenced by genome-wide hypomethylation in SLE CD4+ T cells, particularly at interferon-regulated loci, establishing an epigenetic basis for autoimmune dysregulation." (PMID 40533455, 2025). "CD4+ T cells from patients with systemic lupus erythematosus (SLE) showed an elevated core α1,6-fucosylation compared to healthy individuals." (PMID 41030447, 2025). "Research has demonstrated that CD4+ T cells in lupus-prone mice and SLE patients displayed greater mitochondrial dysfunction and glycolysis metabolism." (PMID 41476956, 2025). "A recent study observed a significant reduction in the RNA expression of NAT10 in CD4+ T cells from systemic lupus erythematosus (SLE) patients compared to healthy controls, along with a decrease in ac4C modification." (PMID 40038243, 2025). "For instance, systemic lupus erythematosus (SLE) patients display reduced NAT10 levels in their CD4+ T cell populations when benchmarked against healthy subjects." (PMID 41472140, 2025). "Stable expression of CD40 protein on cytomembrane vesicles can target CD4+ T cells and inhibit B cell proliferation to treat systemic lupus erythematosus (SLE) through CD40/CD40L interaction blockade." (PMID 40395752, 2025). "Monogenic lupus were distinguished from other familial cases by an even younger age at presentation (6 y vs 19 y, OR = 0.82, P = 2.13 × 10−3), non-biased male-to-female ratio (P = 0.077) and expansion of exhausted CD4+ T cells (CD4+CD45RA+PD-1+) (P = 1.7 × 10−4)." (PMID 40465409, 2025). "These EVs can carry miRNA cargos (miR-155) and induce CD4+ T cell apoptosis, though their role in skin diseases such as bullous pemphigoid (BP) and systemic lupus erythematosus (SLE) remains underexplored." (PMID 40650257, 2025). "In a study of systemic lupus erythematosus (SLE), significant cell pyroptosis was found in CD4+ T cells from patients and SLE model mouse kidneys." (PMID 38273310, 2024). "Moreover, treatment of CD4+ T cells with mitochondrial metabolism inhibitors and glucose metabolism inhibitors reduced interferon-γ production and reversed disease biomarkers in lupus-prone mice." (PMID 38427068, 2024). "This led to a decrease in pro-inflammatory factors and an enhanced anti-inflammatory inhibitory effect on CD4+ T cells, ultimately mitigating the progression of systemic lupus erythematosus (SLE) in MRL/lpr mice." (PMID 39759531, 2024). "Research has demonstrated that CD4+ T cell proliferation is apparent in both the peripheral blood of SLE patients and the renal tubulointerstitial compartment of individuals with proliferative lupus nephritis (PLN)." (PMID 39575238, 2024). "Le lupus systémique était concomitant au diagnostic d'affection à VIH1 (n = 1) ou survenait après initiation du traitement antirétroviral (n = 6), ou d'une nouvelle ligne d'antirétroviral (n = 2) avec un taux de CD4 moyen lors du diagnostic de 284,5/mm3, passant à 578,3/mm3." (PMID 40070975, 2024).
lupus (continued). "promoter and enhancer demethylation may cause CD40LG overexpression on CD4+ T cells in women but not men with lupus." (PMID 38510251, 2024). "Elevated ERV protein levels have also been found in patients with systemic lupus erythematosus (SLE), and autoreactive CD4+ T cells play a principal role in this disease." (PMID 38540701, 2024). "To reveal which subpopulation of CD4+ cells could be modulated in the lupus microenvironment by probiotic-trained MSCs, we used immunostaining and flow cytometry to investigate and compare frequency distribution in Th1, Th2, Th17, and Treg between six experimental groups." (PMID 38072921, 2023). "In general, B cells may play a more crucial role in CD4+ T cell activation in lupus, at least partly due to their chronic activation via the self-antigen-induced stimulation of endosomal TLR7 and TLR9 receptors mediated by the adaptor myeloid differentiation primary response protein 88 (MyD88)." (PMID 38137363, 2023). "In this study, we find that cytotoxic CD4+CD28- T cells are expanded in SLE patients with flow cytometry analysis, and the percentage of CD4+CD28- T cells positively correlates with the Systemic Lupus International Collaborating Clinics/ACR Damage Index (SDI)." (PMID 37415045, 2023). "Additionally, GSEA also revealed an association with immunologic signature terms, including “GSE10325 CD4 T-cell vs lupus CD4 T-cell up”, “GSE19198 1 h vs 24 h IL21 treated T-cell up”, “GSE15930 naïve vs 24 h in vitro stim CD8 T-cell down”, “GSE18893 tconv vs treg 24 h TNF stim up”, etc.." (PMID 37161020, 2023). "Accordingly, overexpression of leptin receptor in SLE CD4 T cells abrogated Tfh cell mal-differentiation and IgG anti-dsDNA generation in humanized lupus chimeras." (PMID 37006245, 2023). "Specifically, in autoimmune diseases like systemic lupus erythematosus (SLE), estrogen stimulates the expression of IL-6, which drives naive CD4 cells to differentiate into Th17 cells and inhibits TGF β of IL-6, which drives naive." (PMID 37215125, 2023). "However, the molecular mechanism underlying the DNA hypomethylation and the upregulation of Dlk1-Dio3 miRNAs in lupus CD4+ T cells remains unclear." (PMID 38153351, 2023). "NFIL3 has a high expression level in CD4+ T cells of patients with systemic lupus erythematosus (SLE) and suppresses the activation and self-reactivity of T cells and subsequent autoimmune response by downregulating CD40L." (PMID 36969166, 2023). "In systemic lupus erythematosus (SLE) patients, the acetylation of histone H3 and H4 was decreased in CD4+ T cells, and the level of histone H3 acetylation was significantly negatively correlated with the SLE severity." (PMID 35274786, 2022). "A recent study in lupus-prone B6.Sle123 and in SLE patients demonstrated that both aerobic glycolysis and mitochondrial oxidative phosphorylation are elevated in CD4+ T cells." (PMID 36389689, 2022). "In systemic lupus erythematosus (SLE), abnormal m5C mRNAs were identified as relevant to critical immune pathways in CD4+ T cells." (PMID 36389669, 2022). "It was found that elevated MBD2 mRNA levels in CD4+ T cells of systemic lupus erythematosus (SLE) patients were positively correlated with the SLE disease activity index." (PMID 36303542, 2022). "It has been reported that lupus CD4+ T cells had altered signaling and function, and the hyperactivation of these cells was an important molecular feature of SLE patients." (PMID 36046235, 2022). "Our data suggested that the inhibited CD40L expression among CD4 + T cells reduced dsDNA antibody concentration in serum and urinary protein in urine of SLE mice, while it alleviated lupus nephritis." (PMID 35001849, 2022). "For example, in systemic lupus erythematosus (SLE), an autoimmune condition where autoreactive CD4+ T cells promote autoantibody formation by B cells, pathogenic T cells increase glucose oxidation and subsequent glucose processing through the TCA cycle." (PMID 36275779, 2022).
lupus (continued). "There exist increased numbers of circulating pre-GC B cells, CCR7loPD-1hiCXCR5+CD4+ T cells, and memory B cells in SLE patients as well as in lupus-like mice, indicating the existence of CD4+ T cell activation and subsequently enhanced GC responses." (PMID 35095344, 2022). "NFIL3 was highly expressed in CD4+ T cells from systemic lupus erythematosus (SLE) patients compared with those from healthy controls, and NFIL3 inhibited the self-reactivity of T cells by decreasing CD40L expression." (PMID 36439145, 2022). "Furthermore, the Helios profile was also altered in other relevant T-cell populations implicated in lupus, such as CD4+ Tregs, conventional CD4+, and double-negative T cells." (PMID 35784310, 2022). "We identified iron accumulation in lupus CD4+ T cells, which was related to the increase in Tfh cells in SLE." (PMID 35499082, 2022). "Loss of methylation of the top probe in the DMR, cg23256579, was reported in peripheral blood cells and purified CD4+ T cells in people assigned female at birth with systemic lupus erythematosus (SLE)." (PMID 35177097, 2022). "Research investigating the connection between circRNAs and CD4+ T cells mainly concentrates on systemic lupus erythematosus (SLE) and asthma." (PMID 35693804, 2022). "CD4+ T cells play an essential role in the pathogenesis of autoimmune diseases, such as systemic lupus erythematosus (SLE)." (PMID 35499081, 2022). "Thus, the downregulation of GDF7 in CD4+ T cells may lead to impaired suppressive functions of lupus Tregs." (PMID 36046235, 2022). "We had previously shown that nanoparticle (NP)-mediated delivery of IL-2 and TGF-β (two cytokines that are deficient in SLE) to mouse CD2+ and CD4+ cells induced tolerogenic immune responses that protected mice from a lupus-like syndrome." (PMID 34122401, 2021). "However, our previous study revealed that despite normal levels of BTLA expression, CD4+ T cells from lupus patients display an altered functionality of the BTLA signaling pathway, and may thus consequently be refractory to Treg-mediated suppression." (PMID 34899718, 2021). "Likewise, NZB/W F1 mice with established lupus show higher pSTAT3 expression in CD4 T cells." (PMID 33572870, 2021). "The subset of T cells in humans that are CD4-/CD8- and αβ TCR+ with pathogenic anti-DNA autoantibody-inducing ability in SLE is interesting, because such Th cells were considered to be unique to MRL-lpr mice with lupus." (PMID 33936042, 2021). "tRF-3009 may participate in metabolic modulation of IFN-α-induced CD4+ T cell OXPHOS in lupus." (PMID 34256772, 2021). "Indeed, in PBMC cultures from inactive lupus patients and healthy subjects, addition of the histone peptide epitopes induced CD4+CD25highFoxP3+ or CD4+CD45RA+FoxP3low Treg cells, as well as CD8+CD25+FoxP3+ Treg cells with stable FoxP3 expression and suppressive activity." (PMID 33936042, 2021). "In accordance with our studies, among IL-10+ CD4 T cells accumulating in lupus-prone mice and SLE patients, phenotypes distinct from Treg and/or CXCR5hiPD1hi TFH were noted." (PMID 33572870, 2021). "The idea of targeting T cell metabolism for lupus therapy has been advocated based on the finding that CD4 T cells in lupus-prone mice had elevated glycolysis and oxidative metabolism that could be normalized with metformin and 2-Deoxy-D-glucose (2DG) treatment resulting in disease improvement." (PMID 34285256, 2021). "We identified 482 differentially expressed tRFs from SLE CD4+ T cells and chose tRF-3009 for further analysis due to its upregulation and the positive correlations between its expression and SLEDAI, active lupus nephritis and serum IFN-α levels." (PMID 34256772, 2021). "Here, we aimed to detect the expression profile of lncRNAs in lupus CD4+ T cells and explore the mechanism that how lincRNA00892 in CD4+ T cells is involved in the pathogenesis of SLE." (PMID 34707498, 2021).